FAP (fibroblast activation protein alpha)
Diseases named in the same sentence as FAP in open-access papers (continued):
Sharing a sentence is not in itself a finding about the gene and the disease.
tumor (continued). "Aggregated data revealed that the elimination of FAPα led to stunted tumor growth and progression and stimulated the immune system to enhance the effects of tumor vaccination." (PMID 25593080, 2015). "In this review, recent progression in the knowledge of the role of FAPα in tumor microenvironments is discussed." (PMID 25593080, 2015). "In this study, we modified tumor cells to express the fibroblast activation protein (FAP), which is highly expressed by CAFs, to potentially improve whole-cell tumor vaccines by targeting both tumor cells and CAFs." (PMID 26394925, 2015). "Second, the studies identified a subgroup of tumors with worse outcome, which is potentially the subgroup in which FAP is overexpressed in tumor cells." (PMID 25775399, 2015). "We used cancer cells from different tumor types and FAP-positive fibroblasts from different origins, including primary TAFs, for the co-culture experiments." (PMID 26053043, 2015). "To investigate the antitumor mechanism of FAPαc vaccine combined with curcumin, we first performed immunohistochemical studies to verify the expression of IDO and FAPα within the tumor tissues." (PMID 26305550, 2015). "Sensitivity analysis by FAP expression in different cells and tumor types were further subjected to sensitivity analyses as subgroups." (PMID 25775399, 2015). "FAP, a member of the serine protease family, selectively expressed on CAFs and cancer cells, exerts a proteolytic activity that supports tumor growth and proliferation." (PMID 25474039, 2015). "In the present review, the current knowledge regarding the role of FAPα in the interaction between cancer cells and the tumor microenvironment, as well as its biological and therapeutic implications, were summarized." (PMID 25593080, 2015). "The data indicated that the majority of stromal fibroblasts of epithelial tumors and certain malignant tumor cells are characterized by an overexpression of FAPα." (PMID 25593080, 2015). "These can be divided into two categories i) those that targets and neutralizes CAFFAP directly and ii) those that utilize FAP expression in tumor stromal cells to deliver a drug to the tumor site." (PMID 26252379, 2015). "Vaccination with tumor cells expressing FAP eliminated solid tumors and tumors resulting from hematogenous dissemination." (PMID 26394925, 2015). "Levels of FAP overexpression ranged between 54% and 93% in stroma tumors and between 50% and 100% in tumor cells." (PMID 25775399, 2015). "On a functional level, FAP features dipeptidyl- and endopeptidase activity and seems to be involved in tumour cell proliferation." (PMID 25852817, 2015). "First, the relation between FAP overexpression and poor OS and tumor lymph node metastasis was closer in the patients with FAP expression in tumor cells." (PMID 25775399, 2015). "This study and others have suggested that FAP overexpression in tumor, particularly in tumor cells, is a potential key marker." (PMID 25775399, 2015). "The therapeutic efficacy of the FAP-expressing tumor cell vaccine was evaluated in established tumor models." (PMID 26394925, 2015). "Mice were treated with the FAP-expressing tumor cell vaccine once weekly for three weeks after the inoculation of tumor cells." (PMID 26394925, 2015). "We found that the number of FAP-positive CAFs in the primary tumor tissues was reduced by the SVVYGLR motif-recognizing anti-OPN mAb on day 40 after inoculation, indicating that OPN is required for the recruitment of FAP-positive fibroblasts to the tumor." (PMID 26597716, 2015). "Based on these findings, we modified a whole-cell tumor vaccine by transducing tumor cells with murine FAP plasmids using the cationic lipid DOTAP to target both tumor cells and CAFs." (PMID 26394925, 2015). "In the current study, we have shown that the genetic modification of a whole-tumor cell vaccine to express FAP resulted in slowing tumor growth and increased survival in mice inoculated with multiple tumor types." (PMID 26394925, 2015).
tumor (continued). "The aim of this study was to assess the relation of FAP expression in CAFs to overall survival in patients with PDAC and to investigate the mechanisms by which FAP activates tumor progression in PDAC." (PMID 26330349, 2015). "The transmembrane serine protease FAPα is highly expressed on the CAFs present in >90% of human epithelial tumors, and plays a significant role in tumor progression and metastasis." (PMID 26305550, 2015). "Taken together, to our knowledge, this is the first report showing that a FAP-modified whole-tumor cell vaccine induced strong protective and therapeutic anti-tumor immunity via CD8+ T cell-mediated killing." (PMID 26394925, 2015). "The stratified analysis according to FAP expression status demonstrated a closer correlation to the patients with FAP overexpression in tumor cells (HRgroup B: 3.87, CI: 1.58–9.48)." (PMID 25775399, 2015). "We found that in mice immunized with FAPαc vaccine and CpG combined with curcumin lavage, the numbers of tumor cells expressing IDO and FAPα were significantly reduced and the tumor stroma was obviously destroyed (red arrow)." (PMID 26305550, 2015). "Targeting FAPα genetically or with vaccines or pharmacological agents has been shown to impair tumor progression in several preclinical cancer models." (PMID 26305550, 2015). "The pooled outcome from all patients indicated that the patients with high FAP expression had a higher ratio of local tumor invasion than those patients with low FAP expression (OR: 4.48, P = 0.007)." (PMID 25775399, 2015). "Further studies regarding FAP inhibition should focus on tumor cells with FAP overexpression instead of only mesenchymal cells." (PMID 25775399, 2015). "By immunologically targeting both tumor cells and FAP-expressing cells for destruction, this study has confirmed and extended these findings." (PMID 26394925, 2015). "A prodrug that consists of a FAP-specific peptide coupled to a cytotoxic analog of thapsigargin, induced stromal cell death in prostate and breast tumor xenografts and decreased tumor volumes by ~70%." (PMID 24567915, 2014). "The present study found that FAP is expressed predominantly in CAFs from the tumor fibrous stroma of HCCs, and is significantly correlated with frequent vascular invasion in scirrhous HCCs." (PMID 25126747, 2014). "Immunohistochemical staining showed a corresponding increase in protein levels of FAP-α in tumour tissues when compared to background tissue." (PMID 24885257, 2014). "Mice inoculated with FAP-transfected HEK293 cells were two to four times more likely to develop tumours compared with vector-transfected HEK293 controls, with a 10- to 40-fold enhancement in tumour growth." (PMID 24885257, 2014). "Fibroblast activation protein-α (FAP-α), known to be expressed by stromal cells, is another protein that has been reported to disrupt anti-tumor immunity." (PMID 24592240, 2014). "Meanwhile, in HCCs with small nest/trabecular pattern, EMA expression was rather diffuse: the tumor cells closely intermingled with CAFs expressing FAP." (PMID 25126747, 2014). "Antibody abrogation of FAP-α enzymatic activity by site-directed mutagenesis of FAP-α was shown to result in a significant reduction in FAP-driven tumour growth in vivo." (PMID 24885257, 2014). "Depletion of FAP inhibited stromagenesis, tumor growth, and angiogenesis in mouse models of lung and colon cancers." (PMID 24567915, 2014). "Little is known about intracellular post-proline cleaving enzymes such as FAP-α in the context of tumour behaviour and growth compared to other extracellular proteases." (PMID 24885257, 2014). "Significant correlation between EMA-expressing tumor cells and FAP-expressing CAFs and their topographic closeness suggests possible cross-talk between tumor epithelial cells and stromal cells in the tumor microenvironment of HCC." (PMID 25126747, 2014). "TGF-β, Twist and FAP were expressed at various levels in the different tumor tissues from CIS to AM." (PMID 25189096, 2014).
tumor (continued). "Expression of FAP-α was characterized in primary tumour samples and in cell lines, along with the effects of FAP-α expression on in vitro growth, invasion, attachment and migration." (PMID 24885257, 2014). "When FAP is exogenously expressed in tumor cells, it is located in membranous protrusions at the leading edge of migrating tumor cells, interacting with β1 integrins and the cytoskeleton." (PMID 24551161, 2014). "This makes FAP an attractive subject when seeking a tumor biomarker or a potential therapeutic target for the disease." (PMID 24520291, 2014). "FAP+ stromal fibroblasts suppress the immune response to tumors, and elimination of FAP+ fibroblasts from tumor stroma unmasks the immune response to cancer and allows the immune system to attack tumors." (PMID 24605102, 2014). "Significant correlation between EMA-expressing tumor cells and FAP-expressing CAFs and their topographic closeness suggest possible cross-talk between epithelial cells and stromal cells in the tumor microenvironment of HCC." (PMID 25126747, 2014). "Previous studies have demonstrated that FAP has an effect on tumor growth, proliferation and invasion." (PMID 24520291, 2014). "Recently, it has been demonstrated that FAP-α is highly expressed on the surface of glioma cells, bone and soft tissue tumour cells." (PMID 24885257, 2014). "All six biphasic MPM samples showed moderate to strong FAP expression on the tumor cells and a strong expression in the stromal compartment." (PMID 23937772, 2013). "Proof of concept for this prodrug approach has been generated for the tumor stroma marker FAP with urokinase plasminogen activator (uPa) and matrix metalloproteinase-2 (MMP2) mediated cleavage of the TNFR1 domain." (PMID 23840967, 2013). "The intent of this study was now to evaluate a vaccine that silences A20, and co-targets FAP-positive CAFs as well as tumor cells." (PMID 24349329, 2013). "FAP expression has been studied extensively by immunohistochemistry in the past and is known to differ between cell types and even within the tumor tissue." (PMID 23937772, 2013). "Taken together, these data support the notion that FAP+ CAFs play immunosuppressive roles in promoting the tumourigenesis of immunogenic tumour cells." (PMID 24216702, 2013). "All three histological subtypes of MPM demonstrated FAP expression by the tumor stroma and by most tumor cells." (PMID 23937772, 2013). "Proof of concept for this strategy was obtained for several target antigens, including the tumor stroma marker FAP, the T-cell surface markers CD7, and the B-cell surface marker CD20." (PMID 23840967, 2013). "While cotargeting of FAP-positive CAFs and tumor cells with a DC vaccine showed a significant delay in tumor growth in one preclinical study, no mechanistic studies were performed." (PMID 24349329, 2013). "FAP-positive CAFs, the central cellular component of the tumor stroma, have emerged as key players in promoting extracellular matrix (ECM) remodeling, vascularization and immunosupression." (PMID 24349329, 2013). "Eight out of eight epithelioid MPM specimens showed faint to strong FAP expression on tumor cells and a moderate to strong expression on stromal cells." (PMID 23937772, 2013). "In total, we discovered FAP expression on tumor cells and stroma in 16 out of 18 patient MPM samples." (PMID 23937772, 2013). "For tumor cells transfected with FAP, tumor formation rate and invasion ability in the nude rat body significantly increase." (PMID 23420648, 2013). "Depletion of FAP-expressing stromal cells impairs growth of an immunogenic tumor via a mechanism dependent on lymphocytes and generates successful therapeutic vaccination in established tumors." (PMID 23554941, 2013). "Garin-Chesa and colleagues had demonstrated FAP expression in 7 MPM samples in the tumor stroma as well as on tumor cells with variable FAP expression levels." (PMID 23937772, 2013).
tumor (continued). "Due to the expression pattern of FAP in malignant tissues FAP specific re-directed T cells have the potential to demonstrate anti-tumor effects besides MPM in a wide variety of different cancers." (PMID 23937772, 2013). "A significant delay and/or protection of tumor outgrowth was detected in the group treated with anti-FAP re-directed T cells, whereas the tumor grew progressively in the control group injected with NY-ESO-1- re-directed T cells." (PMID 23937772, 2013). "Our rational to develop FAP-specific re-directed T cells based on the F19 antibody was to utilize its already clinically proven specificity to target FAP positive tumor tissue combined with the immunological effector function of T cells." (PMID 23937772, 2013). "Targeting CAFs on the basis of their FAP expression has also been achieved by employing oral immunisation with an attenuated Salmonella strain expressing FAP in immunocompetent mouse tumour xenograft models." (PMID 24216702, 2013). "Proof of concept in vitro as well as in vivo for such tumor selective activation was reported for the stromal marker FAP and the proteases uPA and MMP2." (PMID 23840967, 2013). "Two out for four sarcomatoid MPM samples displayed moderate membranous expression of FAP on tumor cells as well as on stromal cells." (PMID 23937772, 2013). "The clinical data, so far, using F19 (murine anti-FAP mAB) or sibrotuzumab (humanized F19) showed antibody accumulation in the tumor tissue indicating target specificity." (PMID 23259649, 2012). "With this strategy, a prodrug is administrated in an inactive form that is proteolytically activated by the FAP present in cancer activated fibroblasts localized in tumor microenvironment." (PMID 22712570, 2012). "Recently a novel immunosuppressive role for FAP-positive fibroblasts has been shown in the tumor environment." (PMID 23335923, 2012). "Next, we analyzed the tumor sections for phenotypic markers generally associated with tumor associated fibroblasts (TAFs), including αSMA, NG2, FAP and FSP." (PMID 22363446, 2012). "When sub-divided, quantitative results of stromal marker expression indicated that the majority of FSP+, FAP+ and F4/80+ stromal populations found within the tumor microenvironment originated from the bone marrow (p<0.01)." (PMID 22363446, 2012). "Correspondingly, >75% of both prospective and in vitro isolated BM MSC populations (the sorted RFP+ cells and in vitro RFP+ MSC) that were recruited to the tumor microenvironment co-expressed FAP and FSP." (PMID 22363446, 2012). "Our data confirm that BM MSC are a source of bone-marrow derived cells and once they are in the tumor microenvironment, a subset will express pathological disease associated markers FSP and FAP." (PMID 22363446, 2012). "One of the most selective proteins for tumor stromal fibroblasts is the Fibroblast Activation Protein (FAP)." (PMID 21668992, 2011). "The role of FAP in the matrix-induced permissive tumor behavior was assessed in Panc-1 cells in assorted matrices by time-lapse acquisition assays." (PMID 21668992, 2011). "The experimental approach used to study the role of FAP in tumor invasion utilized an in vivo-like 3D matrix system that has been shown to effectively recapitulate stromal ECMs from various murine and human tissues." (PMID 21668992, 2011). "Using the CT26 murine CRC model, Kraman and colleagues showed that fibroblast activation protein-α (FAP)-expressing tumour fibroblasts suppressed the tumour-directed adaptive immune response." (PMID 24212801, 2011). "Recently, fibroblast surface protein (FSP) and fibroblast activation protein (FAP) have been reported to distinguish different types of fibroblasts in tumor tissues." (PMID 21957456, 2011). "In summary we concluded that, since the enhanced motility of Panc-1 cells on FAP+ 3D matrices can be significantly reversed by blocking the function of β1-integrins, a potential mechanism of matrix mediated tumor invasion is an attractive possibility." (PMID 21668992, 2011).
tumor (continued). "Previously, we reported that FAP overexpression by tumor cells results in increased tumorigenicity and tumor growth and its enzymatic activity played an important role in the promotion of tumor growth in mouse model." (PMID 21668992, 2011). "Taking FAP as an example, the mRNA expression level of FAP in tumor specimens was 4 times higher than that in normal tissues." (PMID 20529313, 2010). "FAP, therefore, represents a molecular target for talabostat in tumor stroma; but the involvement of FAP in the antitumor effects of talabostat in mouse tumor models is currently unclear." (PMID 19643020, 2009). "To this end, it is noteworthy that other peptidases (including urokinase-plasminogen activator [uPA] and FAP) were among the genes we found to be highly expressed by tumor-derived endothelium." (PMID 18447899, 2008). "Fibroblast activation protein (FAP), as described so far, is a type II cell surface serine protease expressed by fibroblastic cells in areas of active tissue remodelling such as tumour stroma or healing wounds." (PMID 17105646, 2006). "The genetically stable and restricted expression of FAP leads to the establishment of several preclinical strategies for tumour therapy." (PMID 17105646, 2006). "In a Phase I dose-escalation study of sibrotuzumab in patients with FAP-positive advanced and metastatic solid tumors, the antibody rapidly and selectively accumulated within tumor stroma, confirming FAP-expressing CAFs as the pharmacologic target (NCT02209727)." (PMID 41355964, 2026). "FAP is a transmembrane serine protease expressed by reactive stromal fibroblasts and plays a key role in extracellular matrix remodelling, facilitating tumour invasion and metastasis through degradation of structural proteins and modulation of the tumour microenvironment." (PMID 41410015, 2026). "Additionally, there was a trend towards significance when FAP was analysed in tumour‐adjacent benign areas, where elevated expression of FAP has been shown in proliferative inflammatory atrophy (PIA) and reactive fibrotic stroma." (PMID 41410015, 2026). "As FAP is considered a marker for CAFs and may also be expressed in tumour cells across various tissue types, we created a novel AI‐based image analysis model to recognise FAP separately in both tissue compartments (epithelium/stroma)." (PMID 41410015, 2026). "METHODS: The FAP-specific radiotracer [18F]AlF-FAPI-74 was used to monitor CAFs dynamics following precision external beam radiotherapy (RT) in two syngeneic subcutaneous murine tumor models (LLC and CT26)." (PMID 41761350, 2026). "Epithelial FAP expression (relative to epithelium) was also significantly higher in MRI‐visible tumours (mean = 0.0027, IQR = 0.0016) compared to MRI‐invisible (mean = 0.0009, IQR = 0.0008) and benign regions (mean = 0.0008, IQR = 0.0001) (Kruskal–Wallis test, p < 0.001)." (PMID 41410015, 2026). "The heterogeneity of JA may result in pronounced interindividual variability in FAP expression, influenced by clinical factors such as patient age, tumor size, and stage, as well as by fibrotic remodeling processes and EMT activity." (PMID 40694103, 2026). "In addition, FAP (historically described as the membrane‐bound protease seprase) expression has been reported in tumour cells of several malignancies, including pancreatic, gastric, colorectal, breast, and melanoma cancers." (PMID 41410015, 2026). "Tumor-cell FAP promoted invasion and independently predicted significantly poorer recurrence-free survival (RFS), even in early-stage disease (multivariable Cox p = 0.022 for pT1-2), surpassing established biomarkers such as PD-L1 in capturing aggressive biological features." (PMID 41608569, 2026). "Although the exact role of FAP in JA remains unclear, our findings offer insights into FAP’s potential role in tumor development in JA, indicating it may aid tumor progression via EMT and promote angiogenesis." (PMID 40694103, 2026).